MMP1 (matrix metallopeptidase 1)
Diseases named in the same sentence as MMP1 in open-access papers (continued):
Sharing a sentence is not in itself a finding about the gene and the disease.
melanoma (continued). "Indeed, peritumoral injection of CRAMP (the mouse ortologe of LL-37) increased the mRNA expression of CXCL5, IL23A, MMP1, and MMP9 in B16F10 melanoma in vivo, suggesting that LL-37 could enhance pro-angiogenesis in melanoma." (PMID 36980564, 2023). "In addition to MMP-2, CAFs secrete other proteolytic enzymes, including MMP-1, MMP-13, and MMP-14, which sustain melanoma invasion by leading to ECM digestion and formation of “tracks”, that melanoma cells use to move through the tumor mass and eventually leave the primary site." (PMID 34067929, 2021). "Relative to the control (100%), vitamin D at 0.0002, 0.002, 0.02, and 0.2 μM significantly inhibited MMP-1 protein levels to 76%, 69%,77%, and 78% of control (p < 0.05); and significantly inhibited MMP-2 protein levels to 65%, 46%,45%, and 33% of control (p < 0.05), in melanoma cells." (PMID 32150881, 2020). "Since we showed a greater inhibitory effect of the FB/SFN combination on cell migration in the metastatic WM266-4 cell line, we evaluated if SFN and FB could alter the production of collagenase MMP-1, gelatinases MMP-2 and MMP-9 and stromelysin MMP-3 in this melanoma cell line." (PMID 32486135, 2020). "Vitamin D inhibited TGF-β, and VEGF at the protein and mRNA levels, suggesting transcriptional mechanism, and MMP-1, and MMP-2 at the proteins level, suggesting post-transcriptional mechanism; and its effectiveness in inhibiting angiogenic and metastatic potential in melanoma cells." (PMID 32150881, 2020). "Because MMP3 activates the collagenases MMP1, MMP8 and MMP13 that are capable of degrading collagen types I, II, III, V and IX as well as native fibrillary collagen which is crucial for melanoma metastasis, we tested for MMP3 secretion by performing western blot analyses." (PMID 31728131, 2019). "Additionally, ASA-2P-IS-Na significantly suppressed the cellular tyrosinase activity of cultured human melanoma cells and normal human melanocytes, and showed a small inhibitory effect on matrix metalloproteinase-1 (MMP-1) in normal human fibroblasts, whereas ASA did not inhibit MMP-1." (PMID 31357509, 2019). "Performing the same steps for MMP-1, noncontact cocultivation with keratinocytes, BCC cells and melanoma cells led to an increased expression of MMP-1 by fibroblasts." (PMID 34204372, 2021).
lung carcinoma (88 papers, 2004 to 2025). "High expression of MMP1 is a predictor of irAEs; high MMP1 expression is highly associated with irAEs in lung cancer." (PMID 38580797, 2024). "For example, MMP1 overexpression is associated with tumor invasion and metastasis and is involved in the pathogenesis of lung cancer." (PMID 38580797, 2024). "Previous studies align with our findings, as MMP1 has been implicated in lung cancer progression through PCD modulation." (PMID 39744064, 2024). "Overexpression of MMP1 has been observed in various cancers, including lung cancer, and is associated with tumor progression and unfavorable clinical outcomes." (PMID 38409471, 2024). "Another link between IPF and lung cancer resides in the matrix metalloproteinase 1 (MMP1), which shows a high rate of genetic mutations in both of these two pathologies." (PMID 36553114, 2022). "We conducted a meta-analysis to estimate the potential relationship between MMP1-1607 1G>2G polymorphism and lung cancer risk." (PMID 31244308, 2019). "The MMP-1 rs1799750 polymorphism has been investigated in relation to various diseases, such as ovarian cancer, lung cancer, glaucoma and osteoarthritis." (PMID 31652448, 2019). "It has been proved that MMP1-1607 1G>2G polymorphism elevated risk was found regarding lung cancer, colorectal cancer, head and neck cancer and bladder cancer." (PMID 31244308, 2019). "Our study suggested that MMP1-1607 1G>2G polymorphism was a risk factor for developing lung cancer risk." (PMID 31244308, 2019). "In conclusion, this study identified that rs1144393 AG/GG genotypes located in the MMP1 promoter region were associated with increased RILI risk in patients with lung cancer treated with radiotherapy." (PMID 27659527, 2016). "A cohort of 251 lung cancer patients was genotyped for five single nucleotide polymorphisms in the MMP1 promoter region." (PMID 27659527, 2016). "For MMP1-1607 1G/2G, increased lung cancer risk was found among Asians in additive model(OR = 1.34, 95%CI:1.18-1.53) and with model-free approach(ORG = 1.41, 95%CI:1.21-1.65)." (PMID 26198673, 2015). "Based on the model-free approach, significant result was also produced for MMP1 -1607 1G/2G polymorphism and lung cancer risk among Asians(ORG = 1.41, 95%CI:1.21-1.65)." (PMID 26198673, 2015). "Matrix metalloproteinase 1 (MMP-1) is associated with lung cancer growth and invasiveness, and STAT3 aberrantly induces the MMP-1 gene in colorectal carcinomas." (PMID 24833526, 2014). "Recently, some SNPs of MMP-1 have been demonstrated to be significantly associated with increased risk for the development of lung cancer." (PMID 22655095, 2012). "Recent studies carried out in Caucasian and Asian populations found an association between the 2G polymorphism in the MMP1 promoter and an increased risk of developing lung cancer." (PMID 19094243, 2008). "In lung cancer, it has been similarly shown that a genetic factor of the MMP-1 promoter 2G allele increases the risk of cancer that occurs in a tobacco-usage-dependent manner only in cases with a history of tobacco use." (PMID 17919326, 2007). "Results of two separate meta-analyzes, each including 9 studies, indicated that rs1799750 in MMP-1 may be associated with lung cancer risk, but only in Asian populations." (PMID 32765800, 2020). "Here, we tested whether genetic polymorphisms in the MMP1 promoter region might be associated with RILI risk in lung cancer patients treated with radiotherapy." (PMID 27659527, 2016). "Additionally, we were unable to determine the exact molecular mechanisms by which MMP1 promoter polymorphisms lead to RILI in patients with lung cancer." (PMID 27659527, 2016). "Additionally, it has been reported that SNPs of matrix metalloproteinase-1(MMP-1) promoter were associated with risk of radiation-induced lung injury in lung cancer patients with radiotherapy treatment." (PMID 27769064, 2016).
lung carcinoma (continued). "In lung cancer models, it blocks cell migration and invasion in A549 and H460 cells by downregulating MMP-1 and MMP-3." (PMID 40149916, 2025). "MMP1 has been established as a significant biomarker for tumor progression and metastasis across various cancer types, including lung cancer." (PMID 39551792, 2024). "In late NSCLC downregulation of contractile genes such as TAGLN were also observed, but others such as MMP1, MMP9 and SPP1 were found to be upregulated, which have functions in matrix remodelling and invasion and are linked to poor prognosis in lung cancer." (PMID 38582812, 2024). "The validation of the performance of a fabricated biosensor was performed for a human lung cancer cell line (A549), in which an MMP-1 concentration of 800 ng mL−1 was found." (PMID 36671866, 2022). "Poly(triphenylamine rhodanine-3-acetic acid-co-3,4-ethoxylene dioxy thiophene)s incorporated with molybdenum disulfide were reported for the monitoring of matrix metalloproteinase-1 (MMP-1), which is associated with lung cancer." (PMID 36671866, 2022). "Consistently, high levels of MMP1 have been found in the early phases of lung cancer developed in the context of pulmonary fibrosis." (PMID 36553114, 2022). "In our study, we found that miR‐558 has binding sites for MMP1, MMP16, MMP17, and MMP24 3'‐UTRs, and only MMP17 and MMP1 were demonstrated to be significantly downregulated by miR‐558 through targeted regulation in lung cancer cells." (PMID 33190405, 2021). "Licochalcone A inhibits the migration and invasion of human lung cancer cells via the downregulation of MMP1 expression." (PMID 34445346, 2021). "MMP1 is highly expressed in driving tumour progression in aggressive lung cancer and contributes to the migration and invasion of hepatocellular carcinoma cells." (PMID 34445346, 2021). "We concentrated on those genes that revealed a differential expression between IPF and lung cancer, such as higher expression of MMP1 and MMP3 in IPF than ADC, and lower expression of COL4A1 in IPF than in ADC." (PMID 33905434, 2021). "Regardless, this observation is somewhat in agreement with previous findings that insertion of a guanine (G) at nucleotide position 1607 (rs11292517) in the promotor region of MMP1 results in a 2G allele that is a susceptible factor for IPF and lung cancer." (PMID 33046043, 2020). "SQS induces the phosphorylation of Src and ERK1/2 via OPN, resulting in increased expression of MMP1 and subsequent metastasis of lung cancer cells." (PMID 32862200, 2020). "As such, MMP1 is likely to be a candidate target gene that drives malignant transformation from IPF to lung cancer." (PMID 33046043, 2020). "SQS induced the phosphorylation of Src, ERK1/2, and AKT in lung cancer cell lines, but the levels of pSrc, pERK1/2, and MMP1 were decreased after treatment with SKI (Src inhibitor)." (PMID 32862200, 2020). "Serum MMP-1 levels were measured in lung cancer, being significantly increased in patients with malignancy and positively associated with more advanced stages of the disease and shorter survival." (PMID 32425999, 2020). "Further studies are needed to verify association of rs1799750 in MMP-1, rs243865 in MMP-2, rs11568818 in MMP-7, rs2252070 in MMP-13 and rs28366003 in MT2A with breast, colon and lung cancers." (PMID 32765800, 2020). "When only MMP-1 is positive, although lung cancer, prostate carcinoma, hepatocellular carcinoma, and other malignancies are considered, BC should be suspected, particularly in younger women." (PMID 31537868, 2019). "It was shown previously that Rac1 can stimulate MMP-1 production in lung cancer cell lines and enhance invasion in vitro." (PMID 30544910, 2018). "Rac1 can stimulate MMP-1 or MT1-MMP production in lung cancer cell lines and enhance invasion in vitro." (PMID 30544910, 2018).
lung carcinoma (continued). "High levels of expression of MMP-1 have been associated with tumor growth, invasion and metastasis, and MMP-1 levels have been proposed as a marker of poor prognosis in colorectal, breast, and lung cancers." (PMID 28337194, 2017). "Our results led to identification of a novel pathway involving EREG and MMP-1, which contributes to the growth and progression of lung cancer." (PMID 27995036, 2016). "Our results indicated that rs1144393 in the MMP1 promoter region can be a predictor of grade ≥ 2 RILI in lung cancer patients treated with thoracic radiation." (PMID 27659527, 2016). "Our findings also suggest that macrophages in 3D co-culture models not only increase the expression of MMP-1, but also improve the ability of lung cancer cells to promote angiogenesis." (PMID 27232698, 2016). "Knockdown of PRAME decreases the expression of E-Cadherin and promotes the proliferation, invasion, and metastasis of lung cancer cells by regulating multiple critical genes, most of which are related to cell migration, including MMP1, CCL2, CTGF, and PLAU." (PMID 27391090, 2016). "For instance, the SAA1 lung cancer biomarker, neuro-inflammation factor MMP1, the chemokine ligands (C-C motifs) CCL2, CCL5, and CCL20, and cytokines such as IL6, IL8, IL16, were all significantly modulated." (PMID 26950733, 2016). "In the mid to late 1980s, the Biswas laboratory characterized a factor present on lung carcinoma cell membranes that stimulated MMP-1 production by fibroblasts." (PMID 26604323, 2015). "We conducted a meta-analysis, using a comprehensive strategy based on the logistic regression and a model-free approach, to derive a more precise estimation of the relationship between MMP1, MMP2, MMP9 and MMP13 polymorphisms with lung cancer risk." (PMID 26198673, 2015). "Extracellular matrix metalloproteinase inducer (EMMPRIN) was originally characterized as a factor present on lung cancer cells, which stimulated collagenase (MMP-1) production in fibroblasts." (PMID 26604323, 2015). "In summary, these data suggest that higher SIAH2 levels correspond to lower pSTAT3 and less MMP1 expression in human lung cancers." (PMID 24833526, 2014). "In this study we have investigated the effect of polymorphisms in the promoter regions of the three human collagenases (MMP1, MMP8 and MMP13) and the individual risk of developing lung cancer in a group of 501 cases and 510 controls." (PMID 19094243, 2008). "We have investigated the association between three polymorphisms (-1607 1G/2G, +17 C/G and -77 A/G) in the human collagenases MMP1, MMP8 and MMP13 and the risk of development or progression of lung cancer." (PMID 19094243, 2008). "Contrary to results observed for polymorphisms in MMP1 and MMP13, the polymorphism studied in MMP8 was associated with a reduced individual susceptibility to develop lung cancer in our study." (PMID 19094243, 2008). "Increased expression of MMP1 has been observed in the stroma around lung carcinomas, squamous cell carcinomas of the head and neck and colorectal carcinomas." (PMID 15054469, 2004). "Wang and colleagues discovered that miR-210-3p in lung CSC-exo elevates the expression of N-cadherin, vimentin, MMP-9, and matrix metalloproteinase 1 (MMP-1) in lung cancer cells, while simultaneously decreasing E-cadherin expression to promote cell migration and invasion." (PMID 39578849, 2024). "Furthermore, the sensor was used to measure MMP-1 concentration in A549 lung cancer cell culture medium." (PMID 38920581, 2024). "Results of previously published studies demonstrate that the mechanisms of MMP-1 induction could possibly depend on the tumor, but in lung carcinoma they are virtually unknown." (PMID 29463039, 2018). "Finally, clinical data analysis showed that the expression of MMP1 correlated with the stage, recovery, and modality of lung cancer patients." (PMID 27391090, 2016).
lung carcinoma (continued). "We also investigated the functional impact of rs1144393 on MMP-1 expression in lung cancer patients and found that patients with rs1144393 AG/GG genotypes exhibited higher MMP-1 expression in lung tissues and plasma samples relative to patients with the AA genotype." (PMID 27659527, 2016). "In addition to MMP-1, studies have identified MMP-13 as a collagenase that is associated with a high risk of lung cancer." (PMID 25664615, 2015). "A specific MMP-1 allele, the 2G allele, is associated with a higher risk of lung cancer in individuals who have never smoked as well as in patients with the adenocarcinoma subtype of non-small lung cell cancer." (PMID 25664615, 2015). "In conclusion, this work represents the first study in which polymorphisms in this important group of MMPs (MMP1, MMP8 and MMP13) are analyzed together to understand their contribution to lung cancer development and the effect on disease progression and survival in the Caucasian population." (PMID 19094243, 2008). "In this study, we reasoned that polymorphisms in the regulatory regions of the three human collagenases (MMP1, MMP8 and MMP13), affecting the expression level of these genes, might influence the risk and survival of lung cancer patients." (PMID 19094243, 2008). "Higher levels of MMP-1 are found in the serum of patients with pancreatic cancer (mean: 8.7 ± 7.5 ng/mL) compared to healthy subjects (mean: 6.7 ± 4.9 ng/mL; p < 0.0001) and in the plasma of patients with lung cancer (median: 1.78 ng/mL) compared to healthy subjects (median: 0.99 ng/mL; p < 0.001)." (PMID 39682156, 2024). "Numerous reports in the literature have evaluated the utility of combined tumor-related markers for lung cancer detection and, consequently, we tested whether MMP-1, MMP-7 and MMP-9 could provide complementary discrimination and improve the performance of MMP-9." (PMID 29207990, 2017). "Our findings revealed that in lung cancer tissues or cells, five transcription factors—FOXA1, CEBPB, CTCF, LMNB1, and POLR2A—concurrently regulate the transcription of COL5A1, MMP1, and SERPINE1." (PMID 39551792, 2024). "Eventually, a total of four genes including, CD151, MMP1, PVT1, and SKP2 genes were selected as reference genes based on their known functions in lung cancer progression and lymph node metastasis which have been pointed out in the found articles." (PMID 37185598, 2023). "Several reports suggest that MMP1 is indeed upregulated in patients suffering from diseases such as COPD and lung cancer." (PMID 36120307, 2022). "We examined the effects of CFM-F, TLM, and OSM on lung cancer stem cell (SOX2), migration (MMP1), and fibrosis (TGF-β) markers, since cancer stem cells, fibrosis and migration play a certain role in drug resistance development and cancer cell proliferation." (PMID 35745729, 2022). "In the present study, we identified two important MMPs, MMP1 and MMP17, that are the direct target genes of miR‐558 in lung cancer cells." (PMID 33190405, 2021). "Wei et.al demonstrated that overexpression of BTG2 inhibits the protein expression of cyclin D1, MMP-1, and MMP-2, and inhibit the growth, proliferation, and invasiveness of the A549 human lung cancer cell line." (PMID 34861847, 2021). "In future studies, the hsa_circ_0030998/miR‐558/MMP1/MMP17 pathway will be further confirmed and clarified through a series of in vivo experiments and through studies in more lung cancer cells." (PMID 33190405, 2021). "The other MMPs including MMP1, MMP9 and MMP14 were differentially changed in three lung cancer cells depending on specific cell types." (PMID 34253166, 2021). "ACADL, CD36, LPL, and MMP1 were the signature genes in the PPAR pathway that were identified to be shared among IPF and lung cancer." (PMID 33046043, 2020). "Here, we show that lung CSC‐derived exosomes promote the migration and invasion of lung cancer cells, up‐regulate expression levels of N‐cadherin, vimentin, MMP‐9 and MMP‐1, and down‐regulate E‐cadherin expression." (PMID 32396269, 2020).